KCTD11 (potassium channel tetramerization domain containing 11)
Diseases named in the same sentence as KCTD11 in open-access papers (continued):
Sharing a sentence is not in itself a finding about the gene and the disease.
tumor (continued). "To analyze whether the down-regulation of KCTD11 represents a specific feature of MB, as well to other cancers, we performed a wide screening for KCTD11 expression, analyzing 177 human tumor samples and 177 normal matching samples, representing 18 different cancer types." (PMID 20591193, 2010). "Proteomic analysis revealed that SALL4 interacts with REN/KCTD11 (here REN), a substrate receptor subunit of the Cullin3-RING ubiquitin ligase complex (CRL3REN) and a tumor suppressor lost in ~30% of human SHH-MBs." (PMID 38062245, 2024). "We examined the mRNA expression of KCTD11 in 26 pairs of HCC tissues by RT-PCR, KCTD11 was found lower expressed in tumor tissues." (PMID 28465479, 2017). "Multiple tumor suppressor genes like PHF23, EIF5A, KCTD11, MAP2K4 and ALOX15B, have been reported to promote tumorigenesis when lost, indicating that gene expression regulation, signal transduction, arachidonate lipoxygenase and other cellular pathways are altered with the loss of chromosome 17p." (PMID 36750552, 2023). "To further investigate whether the tumour‐suppressive effect of KCTD11 is mediated by the BTB domain, we transfected a WT KCTD11 plasmid and its mutant MYC‐KCTD11‐ΔBTB in A549 cells." (PMID 34453479, 2021). "With the results above, KCTD11 was found to be regulating not a few molecules related to tumor progression, such as Cyclin D1, CTGF, MMP9 and Slug." (PMID 28465479, 2017). "With the hypothesis that KCTD11 is a tumor suppressor in HCC, we start our research from evaluating the expression of KCTD11 in HCC." (PMID 28465479, 2017). "However, whether KCTD11 can promote the degradation of Hippo/YAP and Wnt/β‐catenin and the mechanism by which it may exert tumour inhibition is unknown." (PMID 34453479, 2021). "KCTD11, reported as a tumor suppressor, are still not well understood." (PMID 28465479, 2017).
cancer (7 papers, 2010 to 2025). A tumor composed of atypical neoplastic, often pleomorphic cells that invade other tissues. "The two other identified genes (KDM2B and KCTD11) were found to be involved with neurodevelopmental disorders and cancer, respectively." (PMID 40349045, 2025). "In summary, except for KCTD11, all other NF-κB target genes upregulated in A549 cells due to chronic hypoxia promote cancer progression." (PMID 38674080, 2024). "Previous work from our group demonstrated that epigenetic events, such as methylation, downregulate KCTD11 in cancer." (PMID 25045667, 2014). "It is noteworthy that the chromosomal region 17p13, where KCTD11 localized, is frequently hypermethylated in cancer." (PMID 20591193, 2010). "KCTD11 overexpression in NSCLC has recently been reported to inhibit cancer progression." (PMID 38674080, 2024). "One speculation is that there is crosstalk between mTORC1 and the hedgehog signaling pathways through KCTD11 in cancer." (PMID 31197948, 2019). "Moreover KCTD11 was undetected both in normal and cancer tissues from liver, lymph-node and exocrine pancreas (data not shown)." (PMID 20591193, 2010). "In summary, we reported a dramatic down-expression of KCTD11 protein in several types of cancer." (PMID 20591193, 2010). "Notably, KCTD11 expression is frequently downregulated in several human cancers, including larynx, esophagus, stomach, colon-rectum, urinary bladder, lung, breast, gallbladder, and endometrium and its promoter was found to be methylated in cancer." (PMID 25045667, 2014). "Therefore, the strong down-regulation of KCTD11 in cancers may be due to promoter hypermethylation." (PMID 20591193, 2010).
infection (1 paper, 2016). The state of being infected such as from the introduction of a foreign agent such as serum, vaccine, antigenic substance or organism. "The potassium transporter gene KCTD11 of the in vitro M cells was markedly upregulated after ΔspeG infection, indicating that speG plays a role in suppressing the expression of this potassium transporter of M cells during S. Typhimurium infection." (PMID 27064787, 2016).
prostate (1 paper, 2014). "KCTD11 was previously identified as a suppressor of Hedgehog signaling, and deregulation of this pathway has been extensively implicated in prostate tumorigenesis." (PMID 25045667, 2014). "Moreover, in around 30% of prostate tumoral tissues, KCTD11 expression was observed mainly in the cytoplasm, suggesting that in these cases the protein could be mutated or sequestered by a deregulated protein interactor." (PMID 25045667, 2014).
KCTD11 also shares sentences with these, for which no sentence is quoted: hepatocellular carcinoma (2 papers); bipolar disorder (1); breast carcinoma (1); kidney tumor (1); lymph node metastasis (1); movement disorder (1); neurodevelopmental disorder (1); Obesity (1); schizophrenia (1); thyroid cancer (1).